MVP (major vault protein)
Diseases named in the same sentence as MVP in open-access papers (continued):
Sharing a sentence is not in itself a finding about the gene and the disease.
lung carcinoma (10 papers, 2012 to 2023). "Contrary to lung cancer, in prostate cancer the elevated expression of MVP is associated with a more than 4-fold higher death risk." (PMID 35681764, 2022). "Taken together, these results suggest that MVP be associated with the pathogenesis of lung cancer, especially with adenocarcinoma." (PMID 31092229, 2019). "Major vault protein (MVP), as a gene associated with lung multidrug resistance, is associated with multiple chemotherapy resistances of lung cancer." (PMID 31044552, 2019). "Elevated IL-25 stimulates the expression of MVP and activates the several intracellular processes, including the NF-κB signaling pathway, contributing to chemotherapy resistances of lung cancer cells." (PMID 35681764, 2022). "MVP was found to be identical to the lung resistance-related protein (LRP) which is specifically over-expressed in multi-drug resistance cases of human lung cancer." (PMID 33637972, 2021). "Taken together, we believe that the up‐regulation of IL‐25 induces MVP expression contributing to chemotherapy resistances of lung cancer cells." (PMID 31044552, 2019). "Further study revealed that IL‐25 regulates cisplatin resistance of lung cancer cells by mediating the expression of MVP." (PMID 31044552, 2019). "In the present study, we occasionally found that IL‐25 and MVP expressions both increased in cisplatin‐resistant lung cancer cells (A549/CDDP)." (PMID 31044552, 2019). "To further illustrate how IL‐25 regulates cisplatin resistance of lung cancer cells, we examined the expression of MVP, which is a well‐known multidrug‐resistant protein, in cisplatin‐resistant A549/CDDP cells." (PMID 31044552, 2019). "Together, these findings suggest, in addition to inducting anti‐apoptosis, IL‐25 promotes cisplatin resistance of lung cancer cells partly by activating NF‐κB signaling pathway to increase the expression of MVP." (PMID 31044552, 2019). "To investigate the role of MVP in NSCLC, we examined MVP expression in surgically removed tumors from 120 patients with lung cancer by IHC." (PMID 31092229, 2019). "Yet, our population investigation reveals a better clinical outcome for the high expression of MVP in lung cancer, especially in adenocarcinoma." (PMID 31092229, 2019). "Knockdown of MVP in LLC cells promoted xenografted lung cancer formation in mice, which was accompanied with accelerated tumor cell proliferation and suppressed cell apoptosis in vitro." (PMID 31092229, 2019). "In order to verify if the accelerated lung cancer growth was due to stronger tumor cell proliferation, we performed colony formation assays to determine the role of MVP in cell proliferation." (PMID 31092229, 2019). "MVP (major vault protein) was also known as LRP (lung resistance-related protein), which was firstly discovered as a new 110 kD drug transporter in doxorubicin-resistant lung cancer cells." (PMID 28938696, 2017). "The upregulation of MVP in lung cancer cells is related to interleukin 25 (IL-25) induction." (PMID 35681764, 2022). "In addition, as evidenced to be identical to LRP, MVP contributes to chemotherapy failure in several malignant tumors such as lung cancer, breast cancer, and hepatocellular carcinoma." (PMID 33637972, 2021). "Our results suggest that MVP act as a suppressor of lung cancer." (PMID 31092229, 2019). "Major vault protein (MVP), implicated in the regulation of cellular signaling cascades and multidrug resistance, has been shown to interact with IFNgamma-regulated gene (CD36) in the H65 lung cancer cell model." (PMID 22384118, 2012). "As such, MVP may act as a suppressor for tumorigenesis in lung cancer." (PMID 31092229, 2019). "Thus, the anti-drug resistance of YPFS+GF in DDP-treated lung cancer cells might be mediated by the down regulation of WT1/MVP axis, as well as the downstream anti-apoptotic pathway of mTORC2/AKT signaling." (PMID 30131696, 2018).
lung carcinoma (continued). "When MVP was knocked down in Lewis lung carcinoma (LLC) cells and the MVP suppressed LLC cells were injected subcutaneously into mice, it promoted lung cancer growth and the tumor cell apoptosis was inhibited." (PMID 31092229, 2019).
viral infection (8 papers, 2011 to 2022). "On the contrary, a deficiency of MVP inhibits HCC development induced by viral infection." (PMID 35681764, 2022). "The induction of MVP expression by viral infection upregulates type-I interferon production by enhancing the expression of IRF7 (interferon regulatory factor 7), but not IRF3 (interferon regulatory factor 3)." (PMID 35681764, 2022). "Experiments using Western blotting further confirmed that the MVP protein level was reduced during the virus infection." (PMID 26490959, 2015). "Diverse roles have been proposed for MVP and/or vaults, including roles in drug resistance, cellular differentiation, innate immunity, virus infections, signaling cascades and cell survival." (PMID 21829365, 2011). "MVP was also shown to be involved in a further proinflammatory responses to viral infection." (PMID 33572350, 2021). "In addition, MVP was down-regulated and OAS2 was up-regulated in the lipid rafts of infected HIBCPP cells, both implicated in innate immune response following viral infection." (PMID 33321840, 2020). "In addition, not only vRNA but also MVP was reported to be upregulated during viral infection by human T-cell lymphotropic virus type I (HTLV-I) infection." (PMID 21829365, 2011). "The authors then assessed possible MVP interaction with myeloid differentiation primary response 88 (MyD88), as this factor is recruited by most Toll-like receptors (TLRs) at the level of their cytoplasmic portion in the cascade that, following viral infection, leads to type-I IFN activation." (PMID 33572350, 2021). "MVP triggers production of cytokines, chemokines, and IFN‐1 during viral infection and mediates resistance to Pseudomonas aeruginosa infection." (PMID 34804992, 2021). "In addition, MVP is downstream of TLR signaling pathways and leads to type I IFN production in virus infection." (PMID 34835073, 2021).
colorectal cancer (6 papers, 2011 to 2025). A primary or metastatic malignant neoplasm that affects the colon or rectum. "For instance, MVP overexpression has been reported to promote proliferation and metastasis in prostate cancer, colorectal cancer, and chondrosarcoma." (PMID 40586636, 2025). "USP22 acts as a major transcriptional factor to regulate major vault protein (MVP) drug resistant gene and links to chemotherapeutic failure in colorectal cancer." (PMID 28567015, 2017).
Obesity (6 papers, 2019 to 2025). Accumulation of substantial excess body fat. "In summary, up-regulation of MVP expression in macrophages of visceral adipose tissues was correlated with obesity in both humans and mice, suggesting that MVP be involved in obesity-associated inflammation." (PMID 30996248, 2019). "MVP deficiency, in animal models was associated with increased plasma levels of nonesterified fatty acids, triglycerides, and total cholesterol, and also aggravated obesity and associated IR, hepatic steatosis and atherosclerosis in mice." (PMID 39324112, 2024). "We further demonstrated that obesity amplifies the MVP-associated phenotype." (PMID 30654824, 2019). "In the present study, we have provided a critical proof of principle that MVP, the major component of vaults, may act as an intrinsic inflammatory gatekeeper in macrophages to regulate obesity-associated metabolic disorders and atherosclerosis." (PMID 30996248, 2019). "However, the observation that the pro-obesity effect of MVP deficiency in macrophages was somewhat less prominent compared to that of global MVP deficiency in mice suggests that other sources of MVP may contribute to the early phase of weight-reducing action." (PMID 30996248, 2019). "DOC2A plus TLCD3B, was a top associated pair for BMI (obesity) and IQ (cognitive impairment), consistent with our data in zebrafish, CDIPT plus ALDOA the top pair for BMI, and KCTD13 plus MVP for IQ." (PMID 39988938, 2025). "As a suppressor of IKK–NF-κB signaling, it is intrigued that MVP expression is induced in murine and human macrophages after the onset of obesity." (PMID 30996248, 2019). "As expected, the phenotypes displayed by the MacKO mice were similar to those of MVP KO mice in the obesity-induced inflammation." (PMID 30996248, 2019). "To understand the role of MVP in metabolic diseases, we firstly determined the role of MVP in obesity." (PMID 30996248, 2019). "Both global and myeloid-specific MVP gene knockout aggravates high-fat diet induced obesity, insulin resistance, hepatic steatosis and atherosclerosis in mice." (PMID 30996248, 2019). "In light of the results obtained with mammary adipocytes derived from lean or obese women, we next investigated whether MVP expression is regulated by contact with adipocytes and by obesity in human tumors." (PMID 30654824, 2019). "Obesity may induce an insufficient up-regulation of MVP comparing with a strong induction of inflammatory response in the body." (PMID 30996248, 2019). "Therefore, MVP deficiency may deteriorate HFD-induced obesity and obesity-associated metabolic disorders including insulin resistance, dysregulation of glycolipid metabolism, and liver steatosis in mice." (PMID 30996248, 2019). "It was found that the mRNA expression levels of STAT3, CORO1C, SERPINH1, MVP and ITGB5 were significantly increased in the obesity compared with the control group." (PMID 34248836, 2021).
prostate carcinoma (6 papers, 2021 to 2025). A carcinoma that arises from epithelial cells of the prostate gland. "In prostate cancer, the upregulation of MVP expression was also considered as a putative prognostic biomarker of cancer." (PMID 35681764, 2022). "Recently, research based on proteomic and bioinformatic analyses identified MVP as a prognostic biomarker for fatal prostate cancer." (PMID 35433709, 2021). "Finally, a study of 119 prostate cancer patients revealed a positive correlation between MVP and the immune checkpoint protein B7-H3, highlighting MVP’s key role in the immunoregulation of cancer." (PMID 40004027, 2025).
glioma (5 papers, 2007 to 2023). A benign or malignant brain and spinal cord tumor that arises from glial cells (astrocytes, oligodendrocytes, ependymal cells). "The molecular mechanisms and signals underlying the activation of MVP expression in gliomas are still unknown." (PMID 24243798, 2013). "With regard to gliomas, our present study suggests that such MVP-mediated migration- and survival-promoting functions are also activated during the malignant transformation/progression of astrocytes." (PMID 24243798, 2013). "During malignant transformation or cancer progression MVP expression is initiated or upregulated in various tumours including gliomas." (PMID 24243798, 2013). "Although no GBM studies have so far identifiedthese 22 genes as important biomarkers of survival, two of the genes in this list areassociated with other types of glioma—MVP was found to be overexpressed inganglio-gliomas." (PMID 23142963, 2013). "Based on a large tissue collection, we re-confirm strong MVP expression in gliomas as compared to healthy brain." (PMID 24243798, 2013). "In the present study, we now re-confirm activation of MVP gene expression in human gliomas as compared to normal brain based on extended expression array data sets." (PMID 24243798, 2013). "In accordance, overexpression of MVP in human glioma tissues has also been reported by other groups." (PMID 24243798, 2013). "The MVP gene is a target of the transcription factor GLI family zinc finger 1 (GLI1), which is abnormally active in glioma lines." (PMID 37242681, 2023). "Studies also suggested the involvement of cancer stem cells, major-vault protein (MVP), anti-apoptotic protein BCL2, oncogenes, tumor suppressor genes, and protein kinase C, GRP78/BiP, in glioma chemoresistance." (PMID 22942880, 2012). "High-intrinsic chemoresistance of glioma cells has been reported by us and other groups involving overexpression of known drug-resistance proteins like P-gp, MRP1, and MVP." (PMID 17342095, 2007).
gastric cancer (4 papers, 2019 to 2023). A primary or metastatic malignant neoplasm involving the stomach. "In this respect, MVP phosphorylation in the cellular milieu was first observed in stomach cancer cells and was shown to be effected by Src protein kinase, playing a role in ERK pathway regulation." (PMID 33572350, 2021). "Recently, it was demonstrated that by interacting with major vault protein (MVP), CHD4 encourages gastric cancer cell proliferation and chemoresistance." (PMID 37569598, 2023). "This is consistent with the observation that MVP binds with and inhibits Src kinase activity and, thus, suppresses ERK activation in stomach cancer cells." (PMID 31092229, 2019). "They thus identified MVP as a Src interactor in human stomach tissue and in stomach cancer cells and showed that EGF stimulation triggers Src-dependent MVP phosphorylation, translocation from the nucleus to the cytosol, and colocalization at the perinuclear region." (PMID 33572350, 2021).
lung adenocarcinoma (4 papers, 2019 to 2023). A carcinoma that arises from the lung and is characterized by the presence of malignant glandular epithelial cells. "The increased expression of MVP in lung adenocarcinoma was associated with a better prognosis." (PMID 31092229, 2019). "For instance, MVP is upregulated in lung tumor tissues compared to the adjacent normal lung tissues, as in the cisplatin-resistant lung adenocarcinoma cell line (A549/CDDP)." (PMID 35681764, 2022). "In this study, we found that both IL‐25 and MVP were elevated expressed in cisplatin‐resistant lung adenocarcinoma cell line (A549/CDDP)." (PMID 31044552, 2019). "The role of YB-1 in drug resistance has been confirmed in lung adenocarcinoma cells, and researchers have discovered that targeting the YB-1/MVP axis may help to overcome gefitinib resistance in lung adenocarcinoma patients." (PMID 38037159, 2023). "MVP would be a potential target for novel therapies of lung adenocarcinoma." (PMID 31092229, 2019). "Moreover, the increased MVP expression in lung adenocarcinoma showed a better prognosis." (PMID 35681764, 2022).
osteoporosis (4 papers, 2021 to 2025). A condition of reduced bone mass, with decreased cortical thickness and a decrease in the number and size of the trabeculae of cancellous bone (but normal chemical composition), resulting in increased fracture incidence. "Then, Mvpf/fLyz2-Cre mice were exploited in two osteoporosis contexts, aging and abrupt loss of estrogen, and we revealed that conditional knockout of MVP inhibited osteoclast apoptosis in vivo and in vitro." (PMID 37704623, 2023). "Next, we explored the clinical potential of targeting MVP in osteoporosis mouse models and used an adeno-associated virus (AAV) gene to overexpress MVP locally in mice." (PMID 34158848, 2021). "Given that high levels of osteoclast-mediated bone resorption are not only due to advanced age but also to the abrupt loss of sexual steroids, especially estrogen, we next examined whether depletion of osteoclast MVP plays a role in estrogen deficiency-induced osteoporosis." (PMID 37704623, 2023). "MVP-Fas signaling cascade was identified to positively regulate osteoclast apoptosis, thus preventing osteoporosis." (PMID 37704623, 2023). "Our in-depth and comprehensive discovery of MVP would provide new insight into osteoclast biology and therapeutic targets for osteoporosis." (PMID 37704623, 2023). "To determine the role of osteoclast MVP in aging-induced osteoporosis, we first detected its expression in mouse models." (PMID 37704623, 2023). "To further investigate MVP’s role in regulating osteoporosis in vivo, we used previously established Mvpf/fLyz2-Cre mouse models, which exhibited osteoporotic phenotypes compared to Mvpf/f or Lyz2-Cre mice." (PMID 37704623, 2023). "Collectively, our comprehensive discovery of MVP’s regulatory role in osteoclasts provides new insight into osteoclast biology and therapeutic targets for osteoporosis." (PMID 37704623, 2023). "MVP also affords a greater selectivity than other osteoporosis therapies as it is predominantly expressed in osteoclasts and also involved in the RANKL-induced Ca2+-calcineurin-NFATc1 pathway." (PMID 34158848, 2021). "The protein MVP (major vault protein) has also been found to help reduce inflammatory processes by suppressing the proliferative activity of macrophages in models of atherosclerosis and osteoporosis." (PMID 41369405, 2025). "Moreover, we reported the interaction between MVP and death receptor Fas, and MVP-Fas signaling cascade was identified to positively regulate the apoptosis of osteoclasts, thus preventing osteoporosis." (PMID 37704623, 2023). "Consequently, these results encouraged us to explore the relationship between MVP and apoptosis in osteoclasts and its role in the pathogenesis of osteoporosis." (PMID 37704623, 2023). "Taken together, our results indicated that MVP could be utilized as a novel target to prevent osteoporosis." (PMID 37704623, 2023). "Taken together, MVP may control osteoclast numbers by promoting osteoclast apoptosis in aging-related osteoporosis." (PMID 37704623, 2023). "Finally, we explored the clinical potential of targeting MVP in two osteoporosis mouse models and used an adeno-associated virus (AAV) gene to overexpress MVP locally in mice." (PMID 34158848, 2021). "In osteoclast-related bone diseases such as osteoporosis, manipulation of MVP activity may be an attractive therapeutic target." (PMID 34158848, 2021). "In this study, we provide considerable evidence that MVP is crucial for osteoclast differentiation and function and utilized MVP global knockout (Mvp-/-) and MVP monocyte-specific conditional knockout (Mvpf/fLyz2-Cre) mice, which both exhibited severe osteoporosis phenotypes." (PMID 34158848, 2021). "Our discovery of MVP's role in negative regulation of osteoclasts may pave the way for clinical intervention strategies to treat patients with osteoporosis." (PMID 34158848, 2021).
ovarian carcinoma (4 papers, 2005 to 2025). A malignant neoplasm originating from the surface ovarian epithelium. "Additionally, MVP is upregulated in various tumors, including colorectal and ovarian carcinomas, where its expression is associated with poor prognosis." (PMID 40004027, 2025). "In drug-resistant SCLC cells, MVP overexpression increased vPARP and TEP1 levels and in resistant ovarian carcinoma A2780TR cell line reduction in MVP expression led to decreased vPARP levels." (PMID 40004027, 2025). "Furthermore, a study with ovarian carcinoma patients revealed a notable discrepancy between MVP transcription and translation levels." (PMID 40004027, 2025). "Several reports link PARP4 overexpression with multidrug resistance genes such as MVP, and, in particular, it was shown by IHC methods that higher levels of PARP4 correlate with higher grade ovarian cancer." (PMID 33811746, 2021). "The same investigation also showed that in the resistant ovarian carcinoma A2780TR cell line, MVP knockdown resulted in vPARP downregulation and vice versa." (PMID 33572350, 2021). "Earliest studies have reported that MVP was overexpressed in various non-Pgp MDR cancers like ovarian carcinoma, AML, oral squamous cell carcinoma, and osteosarcoma; it was correlated with poor prognosis of patients and increased potential for metastasis." (PMID 40004027, 2025).
atherosclerosis (3 papers, 2019 to 2025). A disease characterized by the build-up of fatty material and calcium deposition in the arterial wall resulting in partial or complete occlusion of the arterial lumen. "In order to investigate the impact of MVP on atherosclerosis, we generated the MVP and ApoE double knockout (MVPKOApoEKO) mice." (PMID 30996248, 2019). "MVPKOApoEKO mice suffered from larger lesions with more CD68+ plaque area, suggesting that MVP deletion may promote atherosclerosis in mice." (PMID 30996248, 2019).